CGN (cingulin)
Description:
Probably plays a role in the formation and regulation of the tight junction (TJ) paracellular permeability barrier.
Synonyms: KIAA1319
Tractability: Antibody: its Gene Ontology location is reachable by antibodies, with high confidence; the Human Protein Atlas places it where antibodies can reach. PROTAC: ubiquitination databases record sites on it; its protein half-life has been measured.
Gene: Protein-coding gene on chromosome 1 (151,510,139 to 151,538,692, forward strand). Ensembl gene ENSG00000143375.
Subcellular location: Cell junction, tight junction
Subcellular location (Human Protein Atlas): Cell Junctions; Plasma membrane
Pathways (Reactome):
Signal Transduction: TGF-beta receptor signaling in EMT (epithelial to mesenchymal transition)
Gene Ontology:
Molecular function: cadherin binding; protein binding; actin binding; microtubule binding
Biological process: microtubule cytoskeleton organization
Cellular component: bicellular tight junction; cell junction; plasma membrane; myosin complex
Genetic constraint (gnomAD): Loss-of-function variants: 115 observed, 152.66 expected, observed/expected ratio (o/e) 0.75, 90% interval 0.65 to 0.88. The upper end of that interval is the gene's LOEUF score, 0.88, which puts it in group 3 of 6, group 1 being the genes least tolerant of losing a copy. Missense variants: 1,414 observed, 1,538.8 expected, observed/expected ratio (o/e) 0.92, 90% interval 0.88 to 0.96. Synonymous variants: 527 observed, 620.51 expected, observed/expected ratio (o/e) 0.85, 90% interval 0.79 to 0.91.
Homologues: Orthologues: guinea pig CGN (87% identical), mouse Cgn (86% identical), tropical clawed frog cgn (51% identical), zebrafish cgna (35% identical), zebrafish cgnb (33% identical). Paralogues in human: CGNL1 (31% identical), MYH1 (20% identical), MYH3 (20% identical), MYH4 (20% identical), MYH13 (20% identical), MYH2 (20% identical), MYH7B (20% identical), MYH8 (20% identical), MYH10 (19% identical), MYH6 (19% identical), MYH11 (19% identical), MYH7 (19% identical), and 32 more.
Diseases named in the same sentence as CGN in open-access papers:
CGN is named in the same sentence as 42 diseases in open-access papers, as found by Europe PMC text mining. Sharing a sentence is not in itself a finding about the gene and the disease. The quoted sentences say what the papers report.
cyst (4 papers, 2023 to 2024). A sac-like closed membranous structure that may be empty or contain fluid or amorphous material. "In summary, our data suggest that the tethering of NM2B by CGN to TJs plays an important role in cyst morphogenesis in MDCK cells." (PMID 39319625, 2024). "CGN interaction with microtubules and the Rab11-interacting protein FIP5 (RAB11FIP5) was implicated in the regulation of cyst morphogenesis, but the possible role of CGN interaction with NM2 proteins was not investigated." (PMID 39319625, 2024). "Interestingly, although the Rod-1 region of CGNL1 was required to rescue the cyst morphogenesis phenotype, constructs comprising the Rod-1 region of CGN were also effective in rescuing the planar apical network of microtubules." (PMID 37013686, 2024). "Of note, in contrast to other regulators of apical-basal polarity and TJ, such as Cingulin, PATJ-deficient cells establish the AMIS and a single lumen between two and four dividing cells correctly at first but fail to maintain this single lumen later on during cyst development." (PMID 37878054, 2023). "This could be due to redundant functions of CGN and CGNL1, as CGNL1 controls cyst morphogenesis in mCCD cells, in which CGNL1 is abundantly expressed." (PMID 39319625, 2024). "Highlighted Article:The interaction between cingulin and nonmuscle myosin regulates cyst formation of MDCK cells and maintains the nanoscale organization of cingulin." (PMID 39319625, 2024). "It is also important to note that although CGN has also been implicated in organizing the PAN of microtubules in Eph4 cells and regulating cyst morphogenesis, CGN does not interact with CAMSAP3, and CGN-KO mouse tissues do not reveal altered architecture of polarized epithelial cells." (PMID 37013686, 2024).
lung carcinoma (4 papers, 2014 to 2024). "In The Cancer Genome Atlas (TCGA), a low expression of FOXO1 decreased the survival rate not only in lung adenocarcinoma, but also lung cancer (all), whereas a high expression of CGN decreased the survival rate in lung cancer (all)." (PMID 38338691, 2024). "Previous studies have shown that CGN is related to the occurrence of lung cancer, and it is highly expressed in lung adenocarcinoma, but significantly reduced in squamous cell carcinoma." (PMID 35223987, 2022). "CGN inhibits the up-regulation of the expression of antioxidant molecules in the irradiated lung cancer cells, which enhances the radiosensitivity of cancer cells but not to normal cells." (PMID 28415625, 2017). "Thus, CGN is more effective and less toxic than 8 for treating lung cancer and the concentrations of 0.5 and 1 μM were chosen to study the synergistic or adverse effect of cardenolide on radiation." (PMID 28415625, 2017). "Of them, 6 miRNAs (miR-149, miR-205, miR-375, miR-378, miR-422a and miR-708) and 9 target genes (CEACAM6, CGN, CLDN3, ABCC3, MLPH, ACSL5, TMEM45B, MUC1) were validated by quantitative PCR in an independent cohort of 41 lung cancer patients." (PMID 24625834, 2014).
colorectal cancer (3 papers, 2021 to 2024). A primary or metastatic malignant neoplasm that affects the colon or rectum. "The loss of CGN has been implicated in the malignancy of various cancers, including salivary duct adenocarcinoma, osteosarcoma, and colorectal cancer." (PMID 38338691, 2024).
deafness (3 papers, 2023 to 2025). An inherited or acquired condition characterized by the complete loss of the ability to hear from one or both ears. "One interesting model is the cochlear epithelium, where mutations of both cingulin and γ-actin result in altered tissue architecture and cell loss in vivo, leading to deafness." (PMID 40801571, 2025). "Based on our observations, we propose that deafness and hair cell degeneration is due to altered mechanoregulation of the apical and TJ membranes caused by the loss of CGN function." (PMID 39319625, 2024). "The CGN variant associated with deafness (IH) consists of a deletion within exon 20 of the human gene, resulting in a frameshift mutation of 16 residues and a premature truncation of the C-terminal end of the coiled-coil rod domain and globular tail of CGN." (PMID 39319625, 2024). "The deafness-associated cingulin variant affects tight junction membrane mechanics." (PMID 39319625, 2024). "The results indicate that the CGN–NM2 interaction is critical for CGN conformation and its role in morphogenesis and suggest that the IH variant causes deafness by impacting the CGN-dependent regulation of the mechanics of the membrane cortex of auditory epithelial cells." (PMID 39319625, 2024). "Our findings support CGN as a novel deafness gene and indicate that CGN is required for maintenance of the normal apical structure of sensory hair cells in the cochlea and plays a critical role in auditory function." (PMID 37691516, 2023). "In summary, this study reports human CGN as a novel deafness gene in ADNSHL and provides both in vitro and in vivo evidence on the mechanisms of the CGN variant causing hearing loss in human and mouse." (PMID 37691516, 2023). "The tight junction‐related protein Cingulin (CGN) is a novel deafness gene required for maintenance of cochlear hair cell cuticular plates and hair bundles." (PMID 37691516, 2023). "Both the IH mutant and the KO of CGN were reported to affect the morphology of the cuticular plate and hair bundle and induce the degeneration of outer hair epithelial cells after exposure to high frequency sound, leading to deafness." (PMID 39319625, 2024). "We also show that the CGN mutant protein that causes deafness in human and mouse models is localized at TJs but does not bind to NM2B, resulting in decreased TJ membrane tortuosity." (PMID 39319625, 2024). "However, the physiological function of CGN in the auditory system is still unclear, and no CGN mutations have been associated with human diseases, including deafness." (PMID 37691516, 2023). "Moreover, a variant within the C-terminal, NM2-binding region of CGN is associated with deafness in mice and humans, but it is not clear whether this variant binds to NM2B and affects TJ membrane mechanics." (PMID 39319625, 2024).
COVID-19 (2 papers, 2020 to 2022). A disease caused by infection with severe acute respiratory syndrome coronavirus 2. "Cingulin was also found to be downregulated in COVID-19 patients." (PMID 35563537, 2022).
inflammatory bowel disease (2 papers, 2023 to 2025). A spectrum of small and large bowel inflammatory diseases of unknown etiology. "Butyric acid, for example, has been shown to reduce diarrhea caused by intestinal barrier dysfunction, such as inflammatory bowel disease, as well as to increase the levels of occludin and cingulin proteins in HeLa cells." (PMID 37762181, 2023).
lung adenocarcinoma (2 papers, 2022 to 2024). A carcinoma that arises from the lung and is characterized by the presence of malignant glandular epithelial cells. "Both HDAC inhibitors, TSA and Quisinostat, may have potential for use in therapy for lung adenocarcinoma via changes in the expression of CGN and FOXO1." (PMID 38338691, 2024). "Thus, TSA and Quisinostat may have potential for use in therapy for lung adenocarcinoma via changes in the expression of CGN and FOXO1." (PMID 38338691, 2024). "In this study, we investigated the role and regulation of TJ protein CGN and transcription factor FOXO1 in the malignancy of human lung adenocarcinoma compared to normal lung epithelial cells." (PMID 38338691, 2024). "It was found that the downregulation of CGN induced malignancy via upregulation of MEK-dependent CLDN-2, cell metabolism and cell migration in human lung adenocarcinoma A549 cells." (PMID 38338691, 2024). "In the present study, to investigate the effects of CGN and FOXO1 on the malignancy of NSCLC, we used A549 cells as human lung adenocarcinoma and primary human lung epithelial (HLE) cells as normal lung tissues and performed the knockdown of CGN and FOXO1 by siRNAs." (PMID 38338691, 2024). "In conclusion, in human lung adenocarcinoma, the downregulation of CGN induces malignancy via the upregulation of MEK-dependent CLDN-2 and cell metabolism and cell migration, and the downregulation of FOXO1 induces malignancy via the downregulation of CGN and CLDN-4 and cell proliferation." (PMID 38338691, 2024). "In this present study, our findings indicate that the downregulation of CGN and FOXO1 leads to malignant cell proliferation, cell migration, and altered cell metabolism by upregulating CLDN-2 or CLDN-4 through the MAPK/AMPK pathways in human lung adenocarcinoma A549 cells." (PMID 38338691, 2024).
mesothelioma (2 papers, 2019 to 2021). A usually malignant and aggressive neoplasm of the mesothelium which is often associated with exposure to asbestos. "In the ceRNA networks, GAS1RR, AXIN2, AC017104.1, RASSF8-AS1, CGN, MIR4458HG, has-miR-125b-5p, LINC01105, and CASP9 were significantly associated with overall survival in mesothelioma." (PMID 31681739, 2019). "The integrative analysis of genomics and the clinical profiles using the cBioPortal suggested that AXIN2, CASP9, CGN, RASSF8-AS1, and MIR4458HG were highly expressed in mesothelioma compared to some other types of cancer." (PMID 31681739, 2019). "AXIN2, CASP9, CGN, RASSF8-AS1, and MIR4458HG were highly expressed in mesothelioma compared to some other types of cancer." (PMID 31681739, 2019). "AXIN2, CASP9, CGN, RASSF8-AS1, and MIR4458HG were expressed in various mesothelioma cell lines but not in immune cells biomarkers." (PMID 31681739, 2019).
osteosarcoma (2 papers, 2023 to 2024). A usually aggressive malignant bone-forming mesenchymal neoplasm, predominantly affecting adolescents and young adults. "CGN (cingulin), a transmembrane protein localized on the cytoplasmic surface of epithelial tight junctions, has been reported as a tumor inhibitor in ovarian cancer and osteosarcoma." (PMID 36776317, 2023).
ovarian carcinoma (2 papers, 2019 to 2023). A malignant neoplasm originating from the surface ovarian epithelium. "It has been reported that the functions of CLDN4 and CGN are associated with tight junctions, while PVRL4 promotes cell–cell adhesion in ovarian cancer cells." (PMID 31372511, 2019).
breast carcinoma (1 paper, 2022). "In addition, during epithelial-mesenchymal transition in breast cancer model cells, the expression of CGN was observed to be downregulated." (PMID 35223987, 2022).
cavernomas (1 paper, 2020). "However, the tight-junction proteins Claudin-5, and Cingulin, as well as the adherens junction VE-cadherin were not correctly localized at the cell-to-cell contacts in the ECs of the cavernomas of the Pdcd10-ko mice." (PMID 33138917, 2020).
colon cancer (1 paper, 2024). "To minimize the interference caused by endogenous cingulin, we used CRISPR/Cas9 genome editing technology to knockout CGN (CGN KO) and introduced GFP-tagged CGN c.3560C > C and GFP-tagged CGN c.3560C > T mutation into multiple clones of HT-29 colon cancer cells." (PMID 38424547, 2024).
glioblastoma (1 paper, 2024). The most malignant astrocytic tumor (WHO grade IV). "To test whether targeting of CGN by miR-100 and miR-125b can alter the growth characteristics of non-CRC cells, we used the LN-18 glioblastoma line." (PMID 39697634, 2024).
glioma (1 paper, 2024). A benign or malignant brain and spinal cord tumor that arises from glial cells (astrocytes, oligodendrocytes, ependymal cells). "Consistent with our data in LN-18 cells, CGN is not highly expressed in glioma cells within The Cancer Genome Atlas (TCGA)." (PMID 39697634, 2024).
glomerulonephritis (1 paper, 2025). A renal disorder characterized by damage in the glomeruli. "A comparison of the cell-interaction networks between cGN and control samples revealed that PECs exhibited increased interactions with neighboring cell types in glomerulonephritis." (PMID 41028563, 2025).
glomerulosclerosis (1 paper, 2015). A hardening of the kidney glomerulus caused by scarring of the blood vessels. "Renal histology as assessed by periodic acid–Schiff staining revealed that cGN rats had severe glomerulosclerosis and tubular dilation; these changes were significantly attenuated in the cGN + C group as compared with in the cGN + V group." (PMID 26634903, 2015).
hearing loss (1 paper, 2023). "Although potential functional differences of CGN in mice and human cochleae cannot completely be excluded, these studies highlight the importance of gene–environment interactions in the pathogenesis and severity of progressive genetic hearing loss." (PMID 37691516, 2023).
IgG4-related disease (1 paper, 2022). "To examine the roles of p63, CGN and angulin-1/LSR in normal human salivary gland duct epithelial cells, we used HSDE cells derived from salivary gland tissues of patients with IgG4-related disease that were previously reported." (PMID 35681564, 2022).
injury (1 paper, 2022). Damage inflicted on the body as the direct or indirect result of an external force, with or without disruption of structural continuity. "In conclusion, the findings decode a previously unidentified role for a myeloid‐TLR4 dependent Nr4a1/Ear2 negative feedback mechanism in macrophage‐mediated progressive renal injury, implying that activation of Nr4a1‐Ear2 axis can be a novel and effective immunotherapy for anti‐GBM cGN." (PMID 35484716, 2022).
irritable bowel syndrome (1 paper, 2021). Irritable bowel syndrome (IBS) is a chronic functional condition of the lower gastrointestinal (GI) tract characterized by abdominal pain or discomfort and disordered bowel habit (diarrhea, constipation, or fluctuation between the two). "Lack of CGN suppressed the gut epithelial barrier, and it is crucial for the initiation and progression of irritable bowel syndrome, a functional GI disorder without specific biomarkers." (PMID 34830864, 2021).
kidney damage (1 paper, 2016). "To investigate whether the manipulation of gut microbiota in SPF mice might prevent Th17-promoted kidney damage, we orally treated mice with a cocktail of four antibiotics (ampicillin, metronidazole, neomycin, and vancomycin [AMNV]) prior cGN induction." (PMID 27851911, 2016).
nephritis (1 paper, 2025). Inflammation of renal tissue. "IFN-I exacerbates nephritis progression, and mice deficient in IFNAR1 develop a less severe phenotype upon cGN induction." (PMID 40393992, 2025).
non-small cell lung carcinoma (1 paper, 2024). A group of at least three distinct histological types of lung cancer, including non-small cell squamous cell carcinoma, adenocarcinoma, and large cell carcinoma. "However, the roles and regulatory mechanisms of CGN and FOXO1 are unknown in non-small cell lung cancer (NSCLC) and normal human lung epithelial (HLE) cells." (PMID 38338691, 2024).
renal carcinoma (1 paper, 2021). A carcinoma arising from the epithelium of the renal parenchyma or the renal pelvis. "The results showed that EIF4EBP1, FOXM1, PLG, and VWF were highly expressed in renal carcinoma compared with normal renal tissue, and ADAM8, CGN, G6PC, ITIH4, and MMP3 were low in expression in renal carcinoma compared with normal renal tissue." (PMID 33968297, 2021).
renal clear cell carcinoma (1 paper, 2022). "Meanwhile, CGN is also considered as a prognostic gene of ccRCC in renal clear cell carcinoma." (PMID 35223987, 2022).
vasculitis (1 paper, 2021). "Increased colocalisation of GEF-H1 and cingulin was observed in the vessels of vasculitis patients compared to those in healthy skin." (PMID 34345888, 2021). "We used immunofluorescence to analyse the location of GEF-H1 and cingulin in 12 vessels of four healthy controls (three vessels each) and 12 vessels of six vasculitis patients (two vessels each)." (PMID 34345888, 2021). "Therefore, to investigate whether cingulin recruits GEF-H1 to tight junctions during inflammation in vivo, we analysed the location of GEF-H1 and cingulin in the skin biopsies of histologically diagnosed vasculitis patients and healthy skin samples." (PMID 34345888, 2021).